DYNAP (dynactin associated protein)
Description:
Plays a role in the regulation of cell proliferation. Promotes activation of the AKT1 signaling pathway. Promotes phosphorylation of AKT1 at 'Ser-473'.
Synonyms: C18orf26; FLJ39106
Tractability: Antibody: UniProt places it where antibodies can reach, with high confidence; its Gene Ontology location is reachable by antibodies, with high confidence; UniProt predicts a signal peptide or a membrane-spanning region.
Gene: Protein-coding gene on chromosome 18 (54,587,757 to 54,599,493, forward strand). Ensembl gene ENSG00000178690.
Subcellular location: Golgi apparatus membrane; Cell membrane
Gene Ontology:
Molecular function: protein binding
Biological process: activation of protein kinase B activity; cellular response to ergosterol; positive regulation of cell population proliferation; regulation of apoptotic process
Cellular component: Golgi apparatus; plasma membrane; Golgi membrane
Genetic constraint (gnomAD): Loss-of-function variants: 5 observed, 8.59 expected, observed/expected ratio (o/e) 0.58, 90% interval 0.3 to 1.22. That is too few expected variants to judge how well the gene tolerates losing a copy. Missense variants: 255 observed, 231.57 expected, observed/expected ratio (o/e) 1.1, 90% interval 0.99 to 1.22. Synonymous variants: 77 observed, 80.75 expected, observed/expected ratio (o/e) 0.95, 90% interval 0.79 to 1.15.
Homologues: Orthologues: chimpanzee DYNAP (97% identical), macaque DYNAP (88% identical), pig DYNAP (58% identical), rat Dynap (48% identical).
Diseases named in the same sentence as DYNAP in open-access papers:
DYNAP is named in the same sentence as 5 diseases in open-access papers, as found by Europe PMC text mining. Sharing a sentence is not in itself a finding about the gene and the disease. The quoted sentences say what the papers report.
ciliopathy (1 paper, 2018). A genetic disorder of the cellular cilia or the cilia anchoring structures, the basal bodies, or of ciliary function. "Indeed, loss of Heatr2 significantly decreased the FRAP mobile fraction of Ktu in DynAPs (h’), suggesting that an alteration in liquid like behavior is linked to defects in DynAP assembly that in turn associate with defects in cilia beating in an animal model of motile ciliopathy." (PMID 30561330, 2018). "We reasoned that modeling motile ciliopathy might shed light on DynAP function: If DynAPs are sequestering organelles for mis-assembled dyneins, we expect their numbers to increase if DNAAF function is disrupted; if they are assembly organelles, we expect the converse." (PMID 30561330, 2018).
cancer (2 papers, 2015 to 2021). A tumor composed of atypical neoplastic, often pleomorphic cells that invade other tissues. "Since it was established that the splicing pattern of many genes is closely related to tumorigenesis, cancer metastasis, and drug resistance, it is worth investigating the other dynAP isoforms." (PMID 34043884, 2021). "Several human cancer cell lines express dynAP, but expression in normal human tissues is limited in esophagus and spleen, and its physiological function remains to be determined." (PMID 34043884, 2021). "In conclusion, dynAP may be a new target for cancer therapy because it initiates oncogenic cell transformation and facilitates tumor malignancy." (PMID 26284361, 2015). "Thus, dynAP could be a new oncoprotein and a target for cancer therapy." (PMID 26284361, 2015).
tumor (2 papers, 2015 to 2022). "In addition, the cell-cell contact in dynAP-expressing cell-derived tumor tissues appeared to be weaker than that in Ras-expressing cell-derived tissues, which prompted us to examine E-cadherin levels as described later." (PMID 26284361, 2015). "Interestingly, the dynAP-expressing cell-derived tumor tissues showed the highest density of blood vessels and H-Ras repressed the angiogenic potency of dynAP, suggesting interplay between dynAP and H-Ras." (PMID 26284361, 2015). "Thus, tumor formation by NIH3T3H-Ras and NIH3T3H-RasdynAP cells would validate our tumorigenic assay procedures and indicate whether dynAP cooperates with H-Ras in tumor formation." (PMID 26284361, 2015). "Although tumor formation in a model animal system is not necessarily an indication of tumorigenicity in humans, our findings warrant further studies of dynAP as a potential oncoprotein." (PMID 26284361, 2015).
DYNAP also shares sentences with these, for which no sentence is quoted: allergic disease (1 paper); asthma (1).